IRS1 (insulin receptor substrate 1)
Diseases named in the same sentence as IRS1 in open-access papers (continued):
Sharing a sentence is not in itself a finding about the gene and the disease.
Insulin resistance (continued). "Insulin resistance may worsen due to hyperinsulinemia, which then compounds the problem of serine and threonine phosphorylation on IRS-1." (PMID 33995826, 2021). "In insulin resistance, IRS1 malfunctions more often than IRS2." (PMID 34445300, 2021). "The major cause for diet-induced obesity and insulin resistance is the overactivation of mTOR that down-regulates insulin signaling via negative feedback regulation through the phosphorylation of IRS1 at serine residues." (PMID 34445300, 2021). "An increase in adipokines resistin, leptin, PAI-1 and retinol-binding protein 4 in patients with metabolic syndrome and T2D induce insulin resistance in megakaryocytes by interfering with IRS-1 expression, therefore overcoming the inhibitory effects of insulin on platelets." (PMID 34943862, 2021). "An increase in miRNA-143-3p and subsequent suppression of IRS1 may lead to the formation of NASH via the development of insulin resistance and hyperglycemia in the liver." (PMID 34568346, 2021). "In addition, Kelch-like family member 9 (KLHL9) can induce insulin resistance by regulating insulin receptor substrate-1 (IRS1) degradation." (PMID 34516309, 2021). "NNP-2 could improve insulin resistance by modulating the IRS1/PI3K/Akt pathway in insulin-resistant HepG2 cells." (PMID 34071638, 2021). "miRNA-126 can promote insulin resistance by inhibiting IRS1." (PMID 33546399, 2021). "Moreover, loganin attenuated insulin resistance by modulating the JNK-IRS-1 (insulin receptor substrate-1)-Akt-GSK3β signaling pathway in PDN rats." (PMID 34685668, 2021). "This combination of increases in intestinal permeability and plasma LPS levels induce the production of pro-inflammatory cytokines (ILs, TNF-α) and CRP that can in turn induce the serine phosphorylation of insulin receptor substrate-1, leading to insulin resistance." (PMID 34692563, 2021). "Treatment with MH-76 markedly reduced the phosphorylation of IRS-1 at Ser307, which may explain the reduction of insulin resistance and hyperinsulinemia observed in our previous study." (PMID 34069933, 2021). "A previous study revealed crosstalk between adipose tissue and skeletal muscle tissue in obesity-related insulin resistance, and authors found that adipocyte-derived exosomal miR-27a decreased the expressions of IRS-1 and glucose transporter GLUT4 in skeletal muscle tissue by targeting PPARγ." (PMID 33816504, 2021). "The hallmark of insulin resistance in PI3K pathway is the inhibition of the insulin receptors and/or its substrates, especially the insulin receptor substrate 2 (IRS-2) and IRS-1, leading to hyperinsulinemia and hyperglycemia in the peripheral tissues, such as in muscle and adipose tissues." (PMID 33672171, 2021). "However, Ex-4 treatment increased the expression of phosphorylated IRS-1 in neurons under PA-induced insulin resistance." (PMID 33435277, 2021). "Modulation of the insulin cascade at the proximal level involving the insulin receptor and IRS1/2 has gained considerable interest for explaining the pathophysiology of lipid-induced insulin resistance, pinpointing these mechanisms as key drivers of metabolic dysfunction in obesity and T2DM." (PMID 34440850, 2021). "Moreover, in C2C12 myocytes, asprosin treatment augmented insulin resistance by impairing insulin receptor substrate (IRS)-1 and Akt phosphorylation." (PMID 34419063, 2021). "The finding that levels of IRS-1 pSer312 are elevated in blood of PD mice models and blood neuron-derived extracellular vesicles of PD patients may indicate mechanisms of insulin resistance in PD." (PMID 34943038, 2021). "Another mechanism involved in insulin resistance is the increase in IRS-1 serine phosphorylation." (PMID 33918528, 2021).
Insulin resistance (continued). "On the other hand, insulin resistance that cannot be reversed by hyperinsulinemia is often produced by diminished activity of IRS‐1 and its activation of phosphatidylinositol (PI) 3‐kinase (PI3K); this post‐IR defect is provoked by several mechanisms in DIO/MetS/T2DM." (PMID 34766133, 2021). "Similarly, modified SZ can increase tyrosine-phosphorylated insulin receptor substrate-1 (IRS-1) in the skeletal muscle of T2DM rats to relieve insulin resistance." (PMID 33505505, 2021). "Brain insulin resistance is dependent on IRS-1 phosphorylation, and is important in AD pathogenesis as it may potentially be linked to amyloid and tau pathologies." (PMID 34356604, 2021). "In addition, it improved the insulin resistance by inhibiting the expression of the phosphorylated insulin receptor substrate-1 (IRS-1), and by activating the phosphatidylinositol 3-kinase (PI3K)/protein kinase B (PKB or Akt) pathway in IR-HepG2 cells." (PMID 33562762, 2021). "Dephosphorylation of tyrosine residues of IRS-1 and Akt may inactivate the entire process of insulin signaling, leading to insulin resistance." (PMID 34884501, 2021). "This phenolic compound is easily generated by the metabolism of the microbiota after anthocyanin intake, and it was demonstrated that this compound was able to prevent the insulin resistance by increasing p-Tyr-IRS-1 and p-AKT levels in the visceral adipose tissue from obese volunteers." (PMID 34208379, 2021). "However, long-term persistence of high levels of FFA is most likely to promote insulin resistance by inhibiting tyrosine phosphorylation of insulin receptor and IRS-1." (PMID 33841146, 2021). "On the other hand, a relationship between the expression of IRS-1 in L1CAM+ EXOs and systemic insulin resistance was only found in healthy controls (HCs), and sex differences were reported in the serine-312 phosphorylation of IRS-1 in L1CAM+ EXOs in the MDD group." (PMID 33430399, 2021). "In addition, whole body Irs1 knockout mice exhibited severe insulin resistance in skeletal muscle and liver, with compensatory β-cell hyperplasia." (PMID 33763030, 2021). "PP4 forms a complex with IRS-1 and participates in inflammatory-related hepatic insulin resistance." (PMID 34221233, 2021). "Dysregulated secretion of leptin and the increased expression of FoxO1 in propiomelanocortin (POMC) neurons provoke hyperphagia and obesity, as well as hypothalamic hyperactivation of mTORC1, seems to induce hepatic insulin resistance through the inhibition of IRS-1/AKT axis and K (ATP) channels." (PMID 34069890, 2021). "However, Nlrp3 knockout protected mice from the pathological effects of beta-amyloid oligomers and protected against the development of insulin resistance, which was manifested by the unchanged level of expression of IRS1-Ser compared to the control." (PMID 34769018, 2021). "In addition, TNFα induces insulin resistance through serine phosphorylation of IRS-1, with consequent impairment of normal insulin signaling." (PMID 33805912, 2021). "By upregulating secreted frizzled-related protein 4 (SFRP4)—an adipokine which increases insulin resistance by decreasing the abundance of insulin receptor substrate 1 (IRS1) and the FOXO1 transcription factor—these two miRNAs can aggravate insulin resistance in the course of human obesity." (PMID 34943849, 2021). "Reducing total protein intake or BCAAs has been shown to reduce mTORC1 activation in the liver, muscle, and white adipose tissue, and it is generally accepted that chronic hepatic mTORC1 signalling contributes to insulin resistance via the inhibition of insulin receptor substrate-1 (IRS-1)." (PMID 33923531, 2021). "The mechanism by which PRAK knockout induced insulin resistance is likely to be related to the down-regulation of irisin and the suppression of IRS-1, AMPK α, and ERK1/2 phosphorylation since the myocardium of PRAK knockout mice showed reductions in irisin and IRS-1, AMPKα, and ERK phosphorylations." (PMID 34360761, 2021).
Insulin resistance (continued). "Insulin resistance signaling is an exclusively mediated by IRS1 and IRS2 in the liver." (PMID 34449768, 2021). "Based on these results, Ex-4 may promote increased IRS-1 expression and improve insulin resistance in the obese brain." (PMID 33435277, 2021). "They uncovered the exosomes from the IRADE-treated macrophages could contribute to insulin resistance in adipose tissues by decreasing the expression of insulin receptor substrate-1 (IRS-1) and hormone-sensitive lipase (HSL) expression." (PMID 33816504, 2021). "We hypothesized that the IRS1 (Gly972Arg) and IRS2 (Gly1057Asp) genes may influence insulin resistance and are associated with risk of OSA and NAFLD in overweight non-diabetic Asian Indians." (PMID 34449768, 2021). "IRS-1 is also phosphorylated at Ser307 via several mechanisms, including insulin-stimulated kinases or stress-activated kinases like IKKβ, which inhibit insulin signal transduction and contribute to peripheral insulin resistance." (PMID 34959870, 2021). "Inactivation of IR and IRS-1 was identified as the mechanism for insulin resistance." (PMID 34943862, 2021). "Thus, indicating that the alleviation of skeletal muscle insulin resistance is mainly through the regulation of the balance between IRS-1 phosphorylation, thereby reducing its impact on downstream pathways." (PMID 33824679, 2021). "Many factors lead to insulin resistance, including IRS-1 and IRS-2." (PMID 33995826, 2021). "In addition, it increases insulin resistance by acting on insulin signaling through IRS-1 phosphorylation, thus impairing effective translocation of glucose transporter 4 (GLUT4) and insulin-stimulated glucose uptake." (PMID 33919641, 2021). "An additional study found that lysoPC could induce PKC-α activation and inhibit Akt activation in vascular smooth muscle cells (VSMCs) by blocking IRS-1 function suggesting a role for lysoPC in vascular insulin resistance." (PMID 34434168, 2021). "Similarly to muscle and adipose tissue, mTORC1 activity was observed to be increased in the livers of obese rodents, resulting in the degradation of insulin receptor substrate 1 and the onset of hepatic insulin resistance." (PMID 32093387, 2020). "Furthermore, the insulin resistance index (i.e., the ratio of IRS-1-pS312 to IRS-1-pTyr) is significantly increased in the AD condition." (PMID 33203181, 2020). "Activation of protein kinase C by diacylglycerol and advanced glycation end products formed from glyceraldehyde 3-phosphate (in the state of GAPDH activity deficiency) causes phosphorylation (inactivation) of insulin receptor substrate-1 (IRS-1), therefore leading to insulin resistance." (PMID 32709094, 2020). "TNF-α signaling activates intracellular kinases, c-Jun N-terminal kinase and IκB kinase, leading to increased serine phosphorylation of insulin receptor substrate-1 (IRS-1) which impairs insulin signaling, causing insulin resistance that inhibits the transport of glucose into cells." (PMID 33208757, 2020). "Although JNK is known to cause serine phosphorylation of IRS1, which is linked to insulin resistance, loss of the described JNK-induced Ser307 IRS1 phosphorylation actually deteriorates insulin action and metabolism, questioning direct negative effects of JNK activation on insulin action." (PMID 32456175, 2020). "Instead, development of insulin resistance (both in the brain and peripheral tissues) occurs following the inhibitory phosphorylation of IRS1 on specific serine residues, which preclude IRS1 to interact with IR." (PMID 32733190, 2020). "However, BMAT also has lower expression of the IR and IRS-1, suggesting further insulin resistance upstream of GLUT4." (PMID 32555194, 2020). "Increased phosphorylation of IRS-1 on residues Ser307 and Ser612 have been suggested to be responsible for the desensitization mechanisms of insulin-stimulated signal transduction which plays an important role in insulin resistance in obesity." (PMID 33344504, 2020).
Insulin resistance (continued). "Our observation can be supported by the fact that insulin resistance in PCOS women is related to excessive serine phosphorylation of the insulin receptor 1 (IRS-1), and serine phosphorylation modulates the activity of the key regulatory enzyme of androgen biosynthesis, P450c17." (PMID 32182752, 2020). "Moreover, exposure to PM2.5 also induces lipid deposition in the liver and reduces gluconeogenesis, inhibiting insulin receptor substrate 1- (IRS-1-) mediated signaling in the liver, which is associated with insulin resistance and abnormal glucose homeostasis." (PMID 33134393, 2020). "In turn, NF-κB and JNK lead to the impairment of IRS-1 and aggravation of insulin resistance." (PMID 33222694, 2020). "Furthermore, evidence was recently provided that CB1 activation induced by an HFD suppresses the insulin-dependent phosphorylation of Akt through IRS-1 phosphorylation at Ser-307, thereby mediating the emergence of insulin resistance." (PMID 32859125, 2020). "The first evidence of link between inflammation, obesity and insulin resistance was the finding that increased expression of tumor necrosis factor α (TNFα), an inflammatory cytokine, promoted insulin resistance via serine phosphorylation of IRS1." (PMID 32524217, 2020). "In addition, PTP1B levels in skeletal muscle were higher, PTP1B interacted with IRS-1 more and insulin resistance was more severe in 28-week-old rats than in 10-week-old rats." (PMID 32082422, 2020). "Moreover, there have been studies that used microarray data for investigating gene expression levels about insulin resistance induced by mitochondrial dysfunction, reduced mitochondrial density, and increased IRS-1 serine phosphorylation." (PMID 32382544, 2020). "Moreover, IL-6 also promotes the expression of cytokine signaling inhibitor 1 (SOCS1) and SOCS3, thereby degrading IRS-1 and promoting insulin resistance." (PMID 32082422, 2020). "At present, we observed that incubation with palmitate-induced insulin resistance by attenuating insulin-stimulated glucose uptake, the phosphorylation of IRS1 and AKT, and the distribution of GLUT4, but trilobatin prohibited these effects of palmitate in C2C12 myotubes in a dose-dependent manner." (PMID 33062046, 2020). "Additionally, Q3G is reported to be as effective as quercetin in ameliorating insulin resistance by regulating the insulin receptor substrate 1 (IRS-1) function of the endothelium." (PMID 32722185, 2020). "Furthermore, JNK activation was associated with an increased phosphorylation of the insulin receptor substrate-1 (IRS1), which is known to promote insulin resistance." (PMID 32235829, 2020). "Mice with a targeted disruption of the IRS1 gene show either insulin resistance or T2DM." (PMID 32806641, 2020). "Anti-TNFR1-treated NAFLD mice revealed strongly reduced IRS1 phosphorylation which might contribute to the improved insulin resistance observed in these mice." (PMID 32235829, 2020). "The low and high dose of acacetin observably reduced the level of (Ser612) p-IRS-1 (P < 0.01), indicating that the improvement of insulin resistance in SHR(F) rats by acacetin may be related to the inhibition of insulin receptor phosphorylation at Ser612." (PMID 32892299, 2020). "TNFα can activate JNKs and inhibit IRS-1 phosphorylation, leading to insulin resistance." (PMID 32878255, 2020). "Furthermore, iNOS promotes deactivation of downstream nodes of insulin signaling pathways including Akt, IRS-1 and IR, inducing insulin resistance." (PMID 32429195, 2020). "TNFα promotes insulin resistance by the phosphorylation of insulin receptor substrate 1 (IRS1) on serine residues, via the activation of cellular stress-response kinases, including IκB kinase β (IKKβ), c-Jun N-terminal kinase (JNK), and protein kinase RNA-activated (PKR)." (PMID 30837902, 2019). "IRS-1 is a key molecule in insulin signaling and its down-regulation leads to insulin resistance." (PMID 31723029, 2019).
Insulin resistance (continued). "Cardiac biopsies and the investigation of insulin signaling molecules, such as insulin receptor substrate 1 (IRS1), IRS1-associated PI3K (IRS1-PI3K), and GLUT4, may be alternative and direct diagnostic methods to evaluate myocardial insulin resistance." (PMID 31330848, 2019). "The mechanism of improving insulin resistance may be that phillyrin could raise the protein phosphorylation of IRS-1 and Akt and the expression levels of GLUT4 protein." (PMID 31355254, 2019). "Impairment of IRS-1 activation may induce insulin resistance via dependent and independent phosphorylation of Akt." (PMID 31035653, 2019). "Reduction in expression of Insr, Irs1, and AdipoQ may possibly contribute to the severe insulin resistance that developed after a second exposure to HFD." (PMID 31234301, 2019). "Therefore, the intake of fruits reduces the severity of insulin resistance via induction of IRS-1 expression in the liver." (PMID 31171927, 2019). "Murine experiments reveal that targeted depletion of IRS-1 or IRS-2 leads to insulin resistance." (PMID 31920981, 2019). "The evidence above indicated that LPS may affect insulin resistance through IRS-1/PI3K/AKT pathway, thereby regulating the hepatic lipid accumulation." (PMID 31839747, 2019). "Thus, ablation of the IRS-1/2 receptors by overexpression of inflammatory molecules suppresses the insulin signaling pathway and results in insulin resistance." (PMID 31551782, 2019). "The results showed the phosphorylation of tyrosine 632 of IRS-1 after treatment of cells with palmitate (to make the diabetic model of insulin resistance) and stimulation with insulin (to initiate the signal pathway) in TNF-α-downregulated cells was 45% (p < 0.05) higher than the normal cells." (PMID 30863203, 2019). "Previously, we reported that carrageenan induced glucose intolerance and insulin resistance by two distinct mechanisms, including an increase in phospho(Ser307/312)-IRS1, a negative regulator of insulin signaling, and decline in phospho(Tyr)-IRS1, a positive regulator of insulin signaling." (PMID 31179345, 2019). "In addition to these factors, defects in serine phosphorylation of IRS-1 also plays a pivotal role in insulin resistance." (PMID 31035653, 2019). "The observation of a significant IRS-1 tyrosine phosphorylation decrease suggests the possibility of chronic subclinical cellular insulin resistance, which could contribute to the development of HAND." (PMID 30972014, 2019). "IRS-1 is the key molecule in insulin signaling and insulin resistance." (PMID 31723029, 2019). "Decreased IRS-1 expression has been characterized in insulin resistance." (PMID 31723029, 2019). "Moreover, it is likely that this enzyme by affecting the structure and function of proteins such as insulin receptor substrate 1 (IRS1) and serine/threonine-protein kinase 2 (AKT2) as well as by reducing insulin signaling cause insulin resistance." (PMID 31231498, 2019). "In addition, the c-Jun N-terminal kinase (JNK) pathway also stimulates IRS-1 serine phosphorylation in the mice liver, which results in insulin resistance." (PMID 31035653, 2019). "Hepatitis C virus might also induce insulin resistance through insulin receptor substrate-1 serine phosphorylation and upregulated gluconeogenesis." (PMID 31200528, 2019). "This insulin resistance in AT was accompanied by enhanced IRS1 O-linked-glycosamine association in this tissue, but not in the liver and muscle." (PMID 30832230, 2019). "Moreover, F0 HFD mother’s gonads constitutively showed higher inhibition of IRS1, a molecular marker of insulin resistance, which leads to increased nuclear translocation of FOXO3a." (PMID 31641124, 2019). "Therefore, the phosphorylation of IRS-1 at ser307 is considered to be a major player in insulin signaling and insulin resistance." (PMID 30871060, 2019).